G6PD (glucose-6-phosphate dehydrogenase)
Diseases named in the same sentence as G6PD in open-access papers (continued):
Sharing a sentence is not in itself a finding about the gene and the disease.
rhabdomyosarcoma (3 papers, 2016 to 2025). A rare aggressive malignant mesenchymal neoplasm arising from skeletal muscle. "We identified strong correlations between NRF2 and G6PD expression in multiple sarcoma subtypes, including rhabdomyosarcoma, liposarcoma, synovial sarcoma, and MPNST." (PMID 40802750, 2025). "Despite the presence of a pathogenic variant in the X-linked Glucose-6-Phosphate Dehydrogenase gene, no haemolytic crisis occurred before the diagnosis of rhabdomyosarcoma, and no excessive transfusions were necessary during chemotherapy." (PMID 37507557, 2023). "In addition, silencing G6PD expression inhibited, and exogenous G6PD expression increased, proliferation in Rhabdomyosarcoma (RMS) cells, confirming that increased G6PD levels are associated with increases in cell growth." (PMID 27861141, 2016).
sarcoma (3 papers, 2016 to 2025). A usually aggressive malignant neoplasm of the soft tissue or bone. "We next aimed to determine whether there is evidence for NRF2/G6PD axis activation in human sarcomas and other cancers." (PMID 40802750, 2025). "(3B) In CSC and native cells from sarcoma, the NormFinder software identified GAPDH, YWHAZ and 18S rRNA as the most stable genes, instead G6PD, RPL13a and B2M were the less stable." (PMID 26894994, 2016).
septicaemia (3 papers, 2009 to 2024). "Extrapulmonary dissemination and bacteremia were significantly reduced in G6PD-deficient mice 48-h post-infection." (PMID 38559268, 2024).
skin cancer (3 papers, 2024 to 2025). "In skin cancers, G6PD upregulation is frequently observed in primary tumors and metastases, positioning it as a potential target for disrupting cancer metabolism." (PMID 39796677, 2024). "This review examines current knowledge on the correlation between altered glucose-6-phosphate dehydrogenase expression and activity and skin cancer progression, with the aim of identifying a potential therapeutic target for treating advanced skin cancer." (PMID 39796677, 2024). "G6PD inhibition in skin cancer therapy could involve low-dose chemotherapy combinations, offering synergistic effects with reduced side effects." (PMID 39796677, 2024). "We examine the potential roles of G6PD inhibition in the treatment of skin cancer." (PMID 39796677, 2024). "In skin cancer, G6PD expression correlated with the presence of distant metastases during disease development and immune activity in the tissues affected, suggesting G6PD levels could be a biomarker predicting immunotherapy response." (PMID 38115544, 2024). "In this review, we examine the role of G6PD in skin cancer metabolism, with the aim of identifying a novel therapeutic target for a multi-drug approach in the treatment of advanced skin cancer." (PMID 39796677, 2024).
small cell lung carcinoma (3 papers, 2022 to 2025). Small cell lung cancer (SCLC) is a highly aggressive malignant neoplasm, accounting for 10-15% of lung cancer cases, characterized byrapid growth, and early metastasis. "Inhibition of the PI3K/AKT/mTOR pathway promotes G6PD protein degradation, reducing radiotherapy resistance in small cell lung cancer." (PMID 40533802, 2025). "In accordance with our observation, G6PD expression was also increased upon NHW870 treatment in the small cell lung cancer PDX LX-95 model." (PMID 35453346, 2022).
Tumor Lysis Syndrome (3 papers, 2015 to 2024). a group of metabolic abnormalities that can occur as a complication during the treatment of cancer, most commonly after the treatment of lymphomas and leukemias. "The blood G6PD level is checked at baseline as a low G6PD level may influence tumor lysis syndrome prophylaxis and treatment choices." (PMID 26610571, 2015). "The U.S. Food and Drug Administration (FDA) recommends testing for G6PD prior to treatment of tumor lysis syndrome with rasburicase, but the absence of a rapid G6PD test makes this recommendation difficult to follow." (PMID 38132231, 2023).
ANCA associated vasculitis (2 papers, 2015 to 2025). "We report the first case of dapsone induced hemolysis in the setting of a normal G6PD level in a patient with ANCA associated vasculitis which improved after dapsone was discontinued." (PMID 25628986, 2015).
atopic dermatitis (2 papers, 2023). "In contrast, atopic dermatitis rate was similar among G6PD deficient patients and the control group." (PMID 37753082, 2023).
attention deficit-hyperactivity disorder (2 papers, 2023 to 2024). A disorder characterized by a marked pattern of inattention and/or hyperactivity-impulsivity that is inconsistent with developmental level and clearly interferes with functioning in at least two settings (e.g. at home and at school). "ADHD: attention deficit hyperactivity disorder, G6PD: glucose-6-phosphate dehydrogenase." (PMID 39525134, 2024).
B-cell lymphoma (2 papers, 2017 to 2022). "To determine whether PCLP1 induces B-cell lymphoma cell proliferation through PPP, we treated Raji-PCLP1 cells and Raji-Ctrl cells with 6-aminonicotinamide (6AN), a competitive inhibitor of G6PD." (PMID 29245936, 2017).
benign prostatic hyperplasia (2 papers, 2014 to 2022). A non-cancerous nodular enlargement of the prostate gland. "Because previous studies implicated elevated G6PD activity in prostate adenocarcinomas compared with normal or benign prostatic hyperplasia tissues, and G6PD overexpression is observed in several types of cancers, we focused primarily on this rate-limiting enzyme." (PMID 24861463, 2014).
bilirubin encephalopathy (2 papers, 2018 to 2020). "As clinicians and researchers attempt to eliminate acute bilirubin encephalopathy and kernicterus spectrum disorder worldwide, it is essential that agents that are possible triggers for hemolysis in G6PD-deficient neonates be studied both in the lab and in clinical settings." (PMID 33154437, 2020).
bipolar disorder (2 papers, 2024). A disorder of the brain that causes unusual shifts in mood, energy, activity levels and the ability to carry out day-to-day tasks. "Lastly, in the pentose phosphate/glutathione pathways, RPIA was upregulated in bipolar disorder but downregulated in ketosis, whereas G6PD was downregulated in both." (PMID 39125835, 2024). "The ketosis gene expression profile was partially discordant with schizophrenia and bipolar disorder and entirely discordant with major depressive disorder, showing significant downregulation of the genes G6PD, GSR, and RPIA." (PMID 39125835, 2024). "The schizophrenia and bipolar disorder analyses showed an equal ratio of upregulated and downregulated genes, and the magnitude of expression change was greater among the upregulated genes; however, the rate-limiting enzyme G6PD was upregulated in schizophrenia and downregulated in bipolar disorder." (PMID 39125835, 2024).
bronchiolitis (2 papers, 2023). Inflammation of the bronchioles characterized by swelling of the bronchioles and mucus accumulation. "Most infectious diseases tested were significantly more frequent among G6PD deficient subjects than in controls, with odds ratios typically around 1.15, with the notable exception of acute bronchitis/bronchiolitis which had a similar cumulative occurrence of ~28% in the two groups." (PMID 37753082, 2023).
cervical intraepithelial neoplasia (2 papers, 1992 to 2017). "The activities of 6-phosphogluconate dehydrogenase and glucose-6-phosphate dehydrogenase have been measured in squamous epithelial cells of the uterine cervix from normal patients and cases of cervical intraepithelial neoplasia (CIN)." (PMID 1637668, 1992).
chronic myelogenous leukemia (2 papers, 2011 to 2017). "In the chronic myeloid leukemia model (K562Dox) the following 4 DEPs were found to be involved in the GSH metabolism pathway (G6PD, PRDX2, IDH1 and 6PGD), 3 DEPs in the PPP pathway (G6PD, ALDOC and 6PGD) and 2 DEPs in the glycolysis pathway (ALDOC and PKM2)." (PMID 28303926, 2017). "They isolated fibroblasts, granulocytes, and erythrocytes from females of African descent with chronic myelogenous leukemia who were heterozygous for G6PD isoenzymes A and B, separating the isoenzymes by gel electrophoresis." (PMID 23908816, 2011).
Cognitive impairment (2 papers, 2022 to 2023). Abnormal cognition is characterized by deficits in thinking, reasoning, or remembering. "It is found that MA at CV17, CV12, CV6, SP10, and ST36 can increase the activities of hexokinase, pyruvate kinase and glucose 6 phosphate dehydrogenase, and improve the cognitive impairment of rats with MID." (PMID 37397457, 2023).
colitis (2 papers, 2023 to 2025). Inflammation of the colon.
colon adenocarcinoma (2 papers, 2017 to 2022). "Anti-proliferative effect of DHEA coupled with G6PD inhibition was also observed in human colon adenocarcinoma HT29 cells, and DHEA treatment significantly reduced the efficiency of colony formation in soft agar of G6PD-overexpressing cells." (PMID 28553614, 2017).
congenital dyserythropoietic anemia (2 papers, 2020 to 2022). Congenital dyserythropoietic anemia (CDA) is a heterogenous group of hematological disorders of late erythropoiesis and red cell abnormalities that lead to anemia. "Glucose-6-phosphate dehydrogenase (G6PD) and pyruvate kinase (PK), are the most common enzyme deficiencies, and congenital dyserythropoietic anemia (CDA) type II is the best studied form among defective erythropoiesis." (PMID 32655575, 2020).
depression (2 papers, 2022 to 2024). "Major depressive disorder data showed significant downregulation of nine genes, albeit with a relatively lower magnitude of expression change between depression and control groups across datasets and no significant expression changes observed with G6PD." (PMID 39125835, 2024).
diabetic ketoacidosis (2 papers, 2022 to 2024). The metabolic condition resulted from uncontrolled diabetes mellitus, in which the shift of acid-base status of the body toward the acid side because of loss of base or retention of acids other than carbonic acid is accompanied by the accumulation of ketone bodies in body tissues and fluids. "Furthermore, recent studies have shown that increased blood sugar levels such as in diabetic ketoacidosis (DKA) conditions can further impair the function of the G6PD enzyme, causing further cell damage and hemolysis." (PMID 38966448, 2024).
dyspepsia (2 papers, 2020 to 2023). An uncomfortable, often painful feeling in the stomach, resulting from impaired digestion. "Dyspepsia, nausea, and abdominal pain were the most common complaints, in all cases mild and without significant differences between normal and G6PD deficient patients (8.9% vs 13.6%)." (PMID 37510911, 2023).
endometrial carcinoma (2 papers, 2016 to 2017). A malignant tumor arising from the epithelium that lines the cavity of the uterine body. "G6PD levels are elevated in various tumors, including melanoma, leukemia, colon cancers, breast cancers, and endometrial carcinomas." (PMID 27861141, 2016).
endometriosis (2 papers, 2024). The growth of functional endometrial tissue in anatomic sites outside the uterine body. "According to a recent study, FDX1 mediates cuproptosis in endometriosis through the G6PD pathway, which inhibits the proliferation and metastasis of endometriosis cells." (PMID 38397379, 2024).
erythrocyte disorder (2 papers, 2011 to 2015). A disease or disorder that involves the erythrocyte. "We analyzed the variants in Glucose-6-phosphate dehydrogenase (G6PD) and isoforms of Pyruvate Kinase (PKLR & PKM2) genes responsible for major red blood cell disorders." (PMID 21931771, 2011).
familial Mediterranean fever (2 papers, 2020 to 2022). Familial Mediterranean fever (FMF) is an autoinflammatory disorder characterized by recurrent short episodes of fever and serositis resulting in pain in the abdomen, chest, joints and muscles. "In addition, we found a pathogenic variant in MEFV which is associated with familial Mediterranean fever and a hemizygous variant in G6PD, which is associated with X-linked hemolytic anemia." (PMID 34148116, 2022).
gastric tumor (2 papers, 2021 to 2024). "IHC staining and a direct immunoblotting analysis of gastric tumors and their adjacent normal tissues demonstrated that G6PD was overexpressed in gastric tumors, and methylation of H3R17 was at higher levels in tumor specimens than in normal control tissues." (PMID 39266534, 2024). "Consistently, the protein level of G6PD was significantly up-regulated in gastric tumor tissues compared with those in adjacent non-cancerous tissues (P < 0.01)." (PMID 33514309, 2021).
gestational diabetes (2 papers, 2018 to 2023). Carbohydrate intolerance first diagnosed during pregnancy. "Of course, further studies are required to clarify whether leukocyte SIRT1 and G6PD up-regulation might mediate antioxidative effects during gestational diabetes." (PMID 30513672, 2018).
hemoglobinuria (2 papers, 2017 to 2019). A laboratory test result which indicates free hemoglobin in the urine. "Hemoglobinuria was more frequent among G6PD-deficient patients treated with primaquine." (PMID 28605472, 2017).
hyperuricemia (2 papers, 2024 to 2025). An abnormally high level of uric acid. "Due to her worsening dyspnea and AKI, a decision was made to start rasburicase for hyperuricemia while awaiting the G6PD enzyme test result." (PMID 40161169, 2025).
invasive breast carcinoma (2 papers, 2016 to 2023). A carcinoma that infiltrates the breast parenchyma. "Glucose-6-phosphate dehydrogenase (G6PD) expression was evaluated in a tissue microarray from 94 patients with node-positive invasive breast carcinoma and in two publically available databases and correlated with overall survival." (PMID 27078845, 2016). "Finally, we assessed G6PD protein expression with immunohistochemical staining of a tissue microarray from patients with lymph node–positive invasive breast carcinoma, the median follow-up for whom was 12.5 years." (PMID 27078845, 2016).
ischemic stroke (2 papers, 2021). A stroke disorder caused by obstruction of blood flow to the brain, due to thrombotic (local blood clot formation) or embolic (due to a blood clot or other material traveling from another site) event. "The risk of hemoglobin decline should be carefully monitored in G6PD‐deficient patients with ischemic stroke taking aspirin." (PMID 34369077, 2021). "Our recent study suggested that G6PD‐deficient patients had worse functional outcomes at 3 months after ischemic stroke, which was confirmed in this study." (PMID 34369077, 2021). "The protective effect of an older age might partially explain the mild hemolytic symptom in G6PD‐deficient patients with ischemic stroke, as compared with that in younger individuals, but the exact mechanisms need further investigation." (PMID 34369077, 2021).
liver cirrhosis (2 papers, 2020). "A similar observation has been made in studies of liver cirrhosis in rats subject to oxidative stress, where an increase in ME and G6PD gene expression and activity are also seen, presumably providing protection against the stress through an increased production of NADPH." (PMID 32937931, 2020).
lymph node metastasis (2 papers, 2021 to 2025). "Glucose-6-phosphate dehydrogenase (G6PD), the rate-limiting enzyme of the PPP, is overexpressed in OSCC and correlates with advanced disease, lymph node metastasis, and poor prognosis." (PMID 41007256, 2025).
MELAS (2 papers, 2020 to 2022). "Finally, we analyzed the expression differences in proteins involved in oxidative stress: G6PD expression in the skeletal muscle was significantly down-regulated in MELAS patients." (PMID 36254078, 2022).
mesothelioma (2 papers, 2023). A usually malignant and aggressive neoplasm of the mesothelium which is often associated with exposure to asbestos. "Increased levels of H3K9me3 have been observed to repress the expression of glucose-6-phosphate dehydrogenase promoter, reducing the level of tumor-reactive cytotoxic T lymphocytes, and facilitating the growth of human mesothelioma cells." (PMID 37303600, 2023).
metastatic prostate carcinoma (2 papers, 2022 to 2025). A carcinoma that arises from the prostate gland and has spread to other anatomic sites. "Most men with metastatic prostate cancer are treated with ADT as first-line therapy, and therefore, these data indicate that current treatments may in fact be enhancing the G6PD up-regulation seen." (PMID 35213227, 2022).
nasopharyngeal carcinoma (2 papers, 2024). A carcinoma arising from the nasopharyngeal epithelium. "Assay kits were utilized to measure glucose consumption, lactate production, and G6PD activity in nasopharyngeal carcinoma cells." (PMID 39390359, 2024).
Neonatal sepsis (2 papers, 2016 to 2023). Systemic inflammatory response to infection in newborn babies. "The link between G6PD deficiency and infections has been previously recognized in infancy, with lack of G6PD activity identified as a risk factor for neonatal sepsis in males." (PMID 37753082, 2023).
neutropenia (2 papers, 2019 to 2022). A decrease in the number of neutrophils found in the blood. "In addition to inducing hemolysis in G6PD deficient patients, amoxicillin and amoxicillin/clavulanic acid combinations have both been reported to cause neutropenia and pancytopenia in non-G6PD deficient patients being treated for a variety of infections." (PMID 31321386, 2019).
oral cancer (2 papers, 2020 to 2024). "G6PD is overexpressed and has higher activity in different types of tumors, like ovarian, lung, renal, and oral cancer." (PMID 32023830, 2020). "Polydatin, an inhibitor of G6PD, has been shown to inhibit cancer cell growth and reduce lymph node metastasis in HNSCC cell lines and an experimental orthotopic model of oral cancer." (PMID 39796677, 2024).
oral squamous cell carcinoma (2 papers, 2020 to 2024). "They analyzed G6PD expression in 105 patients with oral squamous cell carcinoma (OSCC) by immunohistochemistry and showed that high expression of G6PD was associated with a high lymphatic metastasis rate and poor prognosis." (PMID 39796677, 2024). "G6PD expression in resected oral squamous cell carcinoma (OSCC) samples was analysed by immunohistochemistry." (PMID 32719549, 2020).
ovarian serous cystadenocarcinoma (2 papers, 2022 to 2025). A malignant serous cystic epithelial neoplasm arising from the ovary. "Amongst the proteomics identified and validated genes, the expression of TGFBI significantly positively correlated with the expression of GFPT2, FLNA, G6PD, ITGAV, ITGA1 and ITGA2 within the serous ovarian cystadenocarcinomas in TIMER database." (PMID 36463238, 2022). "METTL3 confers resistance to oxaliplatin by activating G6PD to enhance the pentose phosphate pathway and leads to cisplatin resistance in OSCC, BRCA, ovarian serous cystadenocarcinoma (OV), and LUAD, suggesting the possibility of METTL3 inhibitor combined with platinum chemotherapy drugs." (PMID 41194259, 2025).